ERBB2 (erb-b2 receptor tyrosine kinase 2)
Diseases named in the same sentence as ERBB2 in open-access papers (continued):
Sharing a sentence is not in itself a finding about the gene and the disease.
breast tumors (continued). "To further understand the impact of nuclear expression of KLF6 in ERBB2-overexpressing ductal breast tumors we compare this stain pattern respect to clinico-pathological parameter such as tumor stage, histological grade and size, and lymph node involvement." (PMID 20126619, 2010). "Despite the great progress observed in treating hormone-sensitive and ErbB2-overexpressing breast tumours, the need for further therapeutic targets has been recently emphasised." (PMID 20642837, 2010). "Gene expression analyses classify breast tumors into distinct subtypes, such as luminal A, luminal B, ERBB2-positive (ERBB2+) and basal-like." (PMID 20585577, 2010). "One such inhibitor, INCB7839, has been shown to cooperate with receptor tyrosine kinase inhibitors that target EGFR and ErbB2 to impair breast tumor growth." (PMID 20711474, 2010). "Trastuzumab treatment significantly boosts the prognosis for patients with breast tumours that overexpress ErbB2, but the response rate for these patients is about 50% to 60%." (PMID 18700973, 2008). "Previous immunohistochemical studies on AP-2 and ERBB2 expression in primary breast tumors have reported controversial conclusions." (PMID 18218085, 2008). "The goals of this study were to characterize better the relationship between the overexpressions of ERBB2 and AP-2α in primary breast tumors and to analyze the implication of the YY1 protein as a cofactor of AP-2." (PMID 18218085, 2008). "Our results further suggest that ERBB2 overexpression in breast tumors results not only from a high expression of AP-2α but also from the concomitant high expression of YY1." (PMID 18218085, 2008). "This study highlights the role of both AP-2α and YY1 transcription factors in ERBB2 oncogene overexpression in breast tumors." (PMID 18218085, 2008). "Overexpression of the ERBB2 oncogene is observed in about 20% of human breast tumors and is the consequence of increased transcription rates frequently associated with gene amplification." (PMID 18218085, 2008). "Expression profile analyses have categorized invasive breast carcinomas into five groups: luminal A and B, ERBB2+/ER-, basal-like and normal breast tumors." (PMID 17417968, 2007). "Levels of ESR1 and ERBB2 gene expression were inversely correlated in these samples (r = -0.57, P = 0.0005, Pearson correlation), as has been shown in many other studies of breast tumours." (PMID 17555561, 2007). "The relationship between EGFR and/or ErbB2 overexpression, MAPK hyperactivation, NF-κB transcriptional activity and loss of ER protein expression in Basal-like or ErbB2-overexpressing breast tumours is currently under investigation." (PMID 17700572, 2007). "Referring to our initial data set, breast tumours from patients with IBC showed a higher propensity of belonging to the basal-like or ErbB2-overexpressing cell-of-origin subtype." (PMID 17848951, 2007). "The classification of the breast tumour samples into the different cell-of-origin subtypes was in close agreement with IHC staining results obtained for ER, PR, ErbB2, EGFR and CK5/6, thereby validating our classification." (PMID 17848951, 2007). "ErbB2 protein overexpression was found in 8 out of 12 breast tumours classified as belonging to the ErbB2-overexpressing subtype, whereas for the remaining subtypes only 4 out of 47 breast tumour displayed ErbB2 overexpression (Pearson χ2, P<0.0001)." (PMID 17848951, 2007). "Five out of seven (71%) basal-like, 8 out of 12 (67%) ErbB2-overexpressing, 1 out of 19 (5%) luminal A, 3 out of 8 (38%) luminal B and 2 out of 13 (15%) normal-like breast tumours were IBC samples." (PMID 17848951, 2007). "Five main molecular subtypes (luminal A, luminal B, basal, ERBB2-overexpressing, and normal-like) have been identified by gene expression profiling of breast tumor samples using an intrinsic set of ~500 genes." (PMID 17040570, 2006). "ERBB2 is frequently amplified in breast tumours as part of a wide region of amplification on chromosome 17q21." (PMID 17117180, 2006).
breast tumors (continued). "Consistent with the previously reported frequency of ERBB2 overexpression in primary breast tumors of approximately 30%, four of these 13 primary tumors had a positive Hercep test (2+ or 3+) reported by a clinical lab." (PMID 16457699, 2005). "Garcinol acts as a degradation device to reduce the suppressive activity of regulatory T cells and to enhance the in vivo antitumor activity of a targeted therapeutic anti-p185(her2/neu) (ERBB2) antibody in MMTV-neu transgenics implanted with neu transformed breast tumor cells." (PMID 41303402, 2025). "Very briefly, breast tumors are traditionally classified into Luminal A-like tumors (LumA-l), Luminal B-like tumors (LumB-l), HER2-like tumors (HER2-l), and Basal-like (Basal-l), defined by immunohistochemistry or mRNA levels of key receptors (ESR1, PGR and ERBB2) and proliferative biomarkers." (PMID 41073799, 2025). "In a small case series of breast tumors, we found that presence of an ERBB2 mutation in the absence of amplification was associated with HER2-low IHC (IHC 1+ or IHC 2+/FISH−)." (PMID 40178042, 2025). "91% of ErbB2-positive human breast tumors express CB2 receptors." (PMID 40275168, 2025). "Nevertheless, caution is warranted when considering dietary therapeutic approaches, particularly in scenarios where the ketogenic diet alone may promote ErbB2+ breast tumor growth." (PMID 39097623, 2024). "Moreover, ectopic expression of DECR1 in ErbB2/Neu-induced breast tumor cells is sufficient to reduce ErbB2/Neu expression levels and impair breast tumor growth." (PMID 39403185, 2024). "Likewise, the comparison with murine normal tissues known to express ERα, PR or ErbB2, showed again that the breast tumors developing in Rosa26-RRAS2fl/fl x Wap-Cre mice were negative for the three markers." (PMID 38987766, 2024). "In the early years, Some scholars crossed Ptk6-/- mice with the mouse mammary tumor virus-ERBB2 transgenic mouse line expressing activated ERBB2 and characterized by tumor development and progression, the role of PTK6 in ERBB2-induced breast tumor initiation and metastasis was explored." (PMID 37932734, 2023). "It has been demonstrated that bitransgenic mice that express both activated Akt and ErbB2 in the mammary epithelium show increased breast tumor growth and a significant reduction in lung metastasis when compared to transgenic mice that express only activated ErbB2." (PMID 37195967, 2023). "Besides mAChR, another subtype α9 of nAChR, which interacts with ERBB2 and epidermal growth factor receptor, can also influence intercellular adhesion of breast tumor cells thus mediating the metastasis of breast tumor." (PMID 37773152, 2023). "Delay in ERBB2/NEU (HER2)-induced breast tumor growth in Hsf1-/- mice may result from inhibited cell proliferation of mammary epithelial cells." (PMID 37894333, 2023). "Albeit rare, ERBB2ΔEx16 was implicated mostly in resistance to anti-HER2 agents in HER2-positive breast tumors and osimertinib in EGFR-mutant non-small-cell lung cancer (NSCLC)." (PMID 36686783, 2022). "In addition to the nine isoforms in GENCODE v.30, we detected 36 NIC and 38 NNC distinct spliced isoforms, revealing the complexity of ERBB2 splicing regulation in breast tumors." (PMID 35044822, 2022). "We collected clinical, digital pathology, genomic and transcriptomic profiles of pre-treatment biopsies of breast tumours from 168 patients treated with chemotherapy with or without HER2 (encoded by ERBB2)-targeted therapy before surgery." (PMID 34875674, 2022). "Brain metastasis is common for breast tumours with amplification of the HER2 gene, ERBB2." (PMID 35158800, 2022). "Breast tumors with the overexpression of ERBB2 genes are said to be ERBB2+ (HER2+)." (PMID 34532287, 2021).
breast tumors (continued). "Finally, mice lacking one or both Rlip alleles differentially expressed markers for apoptotic signaling, proliferation, angiogenesis, and cell cycling in PyVT and Erbb2 breast tumors." (PMID 34283045, 2021). "Overexpression of ERBB2 is correlated with poor prognosis and reduced survival in breast tumors." (PMID 32908507, 2020). "The concordance rate of ERBB2 amplification in our study was 85.4%, which indicated that ctDNA could serve as a useful indicator to assess ERBB2 amplification state in breast tumor." (PMID 32908507, 2020). "Given that overexpression of EGFR and ERBB2 by breast tumors predicts a poor prognosis, it might be possible in the future to predict response to IGF1R-directed therapy based on ERBB2/EGFR status." (PMID 32391121, 2020). "Furthermore, MZF1 serine 27 phosphorylation was found to correlate positively and significantly with ErbB2 status in a breast tumor tissue microarray containing 225 tissue cores embedded as duplicates and enriched with primary invasive breast cancer samples." (PMID 31963147, 2020). "Because BC is a heterogeneous disease that is caused by DNA mutations or epigenetic changes, we conjectured that these phenomena could disrupt the connection between SGSM2 and other genes in breast tumours, especially the ERBB2 gene." (PMID 30744493, 2019). "Gene expression analysis showed that MIAT was upregulated in estrogen receptor (ER), progesterone receptor (PR), Erb-B2 Receptor Tyrosine Kinase 2 (HER2) positive breast tumors suggesting that lncRNAs play crucial roles in cell proliferation by targeting the CDKN2A locus." (PMID 31141943, 2019). "However, this approach allowed us to highlight that the high expression of FOXO6 was a marker of poor prognostic in our subpopulation of breast tumors HR- and ERBB2- (triple negative breast tumors) (p = 0.0053)." (PMID 29484124, 2018). "In HER2-positive breast tumors, expression of truncated HER2 isoforms resulting from alternative translation and/or carboxy-terminal fragments (CTFs) resulting from proteolysis (collectively, t-erbB2) have been associated with shortened progression-free survival of patients." (PMID 29872719, 2018). "The overexpression of ERBB2 has been found in breast tumours and correlates with poor prognosis." (PMID 29459674, 2018). "In addition, in vivo testing against ERBB2 overexpressing breast tumours must be conducted to ensure safety profile and efficient CAR-T cells homing towards tumour site." (PMID 28885562, 2017). "Here we show that the ERBB2 oncogene at 17q12 is susceptible to palindromic gene amplification, a mechanism characterized by the inverted (palindromic) duplication of genomic segments, in HER2-positive breast tumors." (PMID 28211519, 2017). "Notably, some of the same proteins were altered, possibly implicating their involvement in the molecular mechanisms by which ErbB2-overexpressing breast tumors metastasize to the brain." (PMID 28174229, 2017). "For example, oncogene addiction effects, such as the increased sensitivity of ERBB2 (HER2)-amplified breast tumors to ERBB2 inhibitors, can be clinically exploited, as can non-oncogene addiction effects, such as the synthetic lethal relationship between BRCA1/BRCA2 mutations and PARP inhibitors." (PMID 28711281, 2017). "Importantly, patients with heterogeneous ErbB2 expression in breast tumors have a worse prognosis than those with a homogeneous ErbB2 expression." (PMID 29285258, 2017). "To assess whether our in vitro results are relevant for in vivo studies, we first applied ioversol CEST pHe in themouse mammary tumor virus (MMTV)-Erbb2 transgenic mouse breast tumor model, which is often used in CEST pHe studies." (PMID 28501855, 2017). "In this study, we seek to determine the mechanism of ERBB2 amplification in primary breast tumors." (PMID 28211519, 2017). "CEP-37440 was also tested in mice harboring SUM190 ErbB2-positive breast tumor xenografts." (PMID 27009091, 2016).
breast tumors (continued). "Over-expression of ERBB2 occurs in approximately 20% of breast tumours." (PMID 27462779, 2016). "Indeed, MMTV-driven overexpression of Ppm1d potentiated Erbb2-induced breast tumor development in mice." (PMID 26883108, 2016). "Moreover, in vitro and in silico evaluations have uncovered ras mutation as a dominant predictor of resistance to PI3K inhibitors in cancers of different origin including breast tumours overexpressing ErbB2 (refs 49, 50, 51)." (PMID 27255951, 2016). "In addition, another group also suggested that modulation of glycolysis targeting the upstream regulator of Akt ubiquitination resensitizes ErbB2-positive breast tumors to trastuzumab." (PMID 26158266, 2015). "Approximately 20 percent of breast tumors are driven by amplification of HER2 (HER2/ERBB2/NEU)." (PMID 26181325, 2015). "Interestingly, treating trastuzumab-resistant cells with metformin re-sensitizes cells by disrupting the ERBB/IGF1R complexes, again strongly suggesting that a combined therapy would hold promise for patients with ERBB2+ breast tumors." (PMID 25964777, 2015). "A proposed molecular profile approach for breast tumor classification defines distinct molecular subtypes of the disease based on differences in the expression patterns of estrogen receptor (ER), progesterone receptor (PR) and HER2 (ERBB2)." (PMID 25743390, 2015). "ERBB2 is a receptor tyrosine kinase that is overexpressed in over 30% of breast tumors." (PMID 25596742, 2015). "Considering that NF-κB is activated by epidermal growth factor receptors (EGFR), the amplification of the EGFR gene HER2/ERBB2/neu in a significant fraction of human breast cancers may provide a partial explanation for downregulation of KLF2 in breast tumors." (PMID 26416422, 2015). "Thus, our results provide rationale for therapeutic evaluation of the treatment of hypoxic ERBB2 expressing breast tumors with a combination of lapatinib and MEK inhibitors." (PMID 25596742, 2015). "Two of the most strongly affected alternative exons in murine NSCs,Myo18a exon 38 and Erbin exon 21 (Erbb2ip, a direct binding-partner of the breastcancer oncogene HER2/Erbb2) were conserved in the human genome and detected in thetranscriptomes of all analyzed breast tumors and controls." (PMID 25380226, 2014). "We also report a significant inverse correlation between ERBB2 expression and both MBP-1 (r= −0.278, p= 0.031) and HDAC1 (r= −0.267, p= 0.037) protein levels in primary breast tumors, and, accordingly, we propose MBP-1/HDAC1/ERBB2 relative expression as a diagnostic marker in breast IDC." (PMID 23421821, 2013). "Furthermore, HSF1 was found required for the cell transformation and tumorigenesis induced by the ERBB2 (aka HER2) oncogene (see subsequent discussion of HER2 amplicon) responsible for aggressive breast tumors." (PMID 23468608, 2013). "Indeed, some breast tumors with copy number changes in both ERBB2 and FGFR1 were recently described." (PMID 23343422, 2013). "Data are already available that show that expression profiling can be used to distinguish cell type-specific gene clusters (stromal, epithelial, mesenchymal and proliferation status) and to classify breast tumors as basal-like, luminal-like, ERBB2 overexpressing and normal breast-like." (PMID 23599813, 2013). "In present, data are available that show that gene expression profiles can be used to distinguish cell type-specific gene clusters (stromal, epithelial, mesenchymal and proliferation status) and to classify breast tumors as basal-like, luminal-like, ERBB2 overexpressing and normal breast-like." (PMID 23599813, 2013). "Moreover, loss of ErbB3 function has been shown to eliminate the transforming capability of ErbB2 (also known as HER-2) in breast tumours." (PMID 23835063, 2013). "In this regard, it is noteworthy that ERBB2 amplification is absent in breast tumors from BRCA1 mutation carriers." (PMID 23181561, 2012).
breast tumors (continued). "Previous studies have shown that based on their mRNA expression breast tumors could be divided into five subgroups (Luminal A, Luminal B, Basal, ErbB2+ and Normal-like), each with a distinct molecular portrait." (PMID 22616941, 2012). "Additionally, gene expression profiling of 213 primary breast tumors with known HER2/ERBB2 status identified PADI2 as one of 29 overexpressed genes in HER2/ERBB2+ tumors; thus, helping to define a HER2/ERBB2+ gene expression signature." (PMID 23110523, 2012). "Such complex regions could be fragile and play a mechanistic role in the amplification of the ERBB2 gene in breast tumors, because repeated sequences are known to initiate gene amplification in model systems." (PMID 23181561, 2012). "In breast tumours, continued expression of AP-2α has been correlated with a better prognosis, but this is hard to reconcile with a reported role in the upregulation of the ERBB2 oncogene." (PMID 21375726, 2011). "Our data suggest that a combined inhibition of Notch and ErbB-2 signalling pathways could decrease recurrence rates for ErbB-2-positive breast tumours and may be beneficial in the treatment of recurrent trastuzumab-resistant disease." (PMID 21847123, 2011). "These methods use a single probe set to predict ER, PR or ERBB2 status of breast tumor samples." (PMID 22022496, 2011). "Here, we used three preclinical xenograft models in vivo, trastuzumab-sensitive, trastuzumab-resistant, and lapatinib-sensitive xenografts, to investigate the anti-tumour benefit of combining trastuzumab or lapatinib plus a GSI on the growth of ErbB-2-positive breast tumours." (PMID 21847123, 2011). "The highest expression of ERBB2 was observed in breast tumor cell lines, as expected." (PMID 21318160, 2010). "Consequently, extensive efforts should be made to find novel agents for the treatment of ErbB2-positive breast tumors." (PMID 20649976, 2010). "Interestingly, though ERBB2 expression level varied in different breast tumor samples, tissues having a nuclear localization of KLF6 show higher expression of ERBB2, as observed in both tissues lots." (PMID 20126619, 2010). "Moreover, our results also (i) show that an elevated percentage of high grade ErbB2-positive human breast tumors express CB2 receptors, and (ii) that a very low fraction of them express CB1 receptors." (PMID 20649976, 2010). "Interestingly, KLF6 was extensively detected in the nucleus of HER-2/ERBB2-overexpressing breast tumor cells whereas it was mainly cytoplasmic in the normal tissue counterpart." (PMID 20126619, 2010). "Our findings suggest that dysregulated ErbB signalling can account for changes in the expression of these genes, and may thus contribute to the establishment and progression of ErbB2-overexpressing breast tumours." (PMID 20840765, 2010). "Our cell model suggests that BCAR4-positive breast tumours are driven by ERBB2/ERBB3 signalling." (PMID 20859285, 2010). "Further, it suggests that TXNIP and TXNRD1 are ERBB2 effectors whose multiple cellular functions contribute to proliferation, apoptosis resistance, metabolic reprogramming and, finally, to the hallmarks of ERBB2-positive breast tumors." (PMID 20584310, 2010). "With this in mind, future validation work should involve testing of candidate genes in other clones, mammary cell lines or breast tumour samples that overexpress ErbB2 and by RNAi-mediated knockdown of ErbB2 expression to see if the observed effects can be reversed." (PMID 20840765, 2010). "The purpose of this study was to determine whether cannabinoids might constitute a new therapeutic tool for the treatment of ErbB2-positive breast tumors." (PMID 20649976, 2010). "However, a substantial number of breast tumors assigned to the ERBB2 subtype lacks ERBB2 protein expression and/or ERBB2 gene amplification and ERBB2-positive cancers that express estrogen receptor (ER) fall into the luminal subtypes." (PMID 20932292, 2010).